IRF4 (interferon regulatory factor 4)
Diseases named in the same sentence as IRF4 in open-access papers (continued):
Sharing a sentence is not in itself a finding about the gene and the disease.
non-small cell lung carcinoma (7 papers, 2020 to 2024). A group of at least three distinct histological types of lung cancer, including non-small cell squamous cell carcinoma, adenocarcinoma, and large cell carcinoma. "For instance, in non-small cell lung cancer, IRF4 is overexpressed and enhances tumorigenesis partially through Notch-Akt signaling." (PMID 37491232, 2023). "IRF4 was overexpressed and activated the cancer progression by Notch signaling pathway in human non-small-cell lung cancer." (PMID 35993041, 2022). "The interferon regulatory factor 4 (IRF4) was overexpressed in non-small cell lung cancer (NSCLC) including both lung adenocarcinoma and squamous cell carcinoma, but not in lung small cell carcinoma, indicating its potential role for the differentiation of NSCLC from small cell lung cancer." (PMID 33287876, 2020). "IRF4 might activate the Notch-Akt signalling pathway in non-small cell lung cancer." (PMID 34109184, 2021).
acute lymphoblastic leukemia (6 papers, 2017 to 2025). Leukemia with an acute onset, characterized by the presence of lymphoblasts in the bone marrow and the peripheral blood. "For instance, the rs12203592 intronic polymorphism in the interferon regulatory factor 4 (IRF4) gene was associated with an increased risk of acute lymphoblastic leukemia." (PMID 40429751, 2025). "An intronal polymorphism in IRF4 is associated with increased risk of male acute lymphoblastic leukemia, wherein the C to T substitution increases IRF4 gene expression by transcriptional repression." (PMID 29299175, 2017). "In a case-control study of childhood leukemia increased IRF4 expression was higher in immature B-common acute lymphoblastic leukemia and T-cell leukemia with the highest expression levels in pediatric AML patients compared to controls." (PMID 34220922, 2021). "However, IRF4−/− mice do not generate pre-B acute lymphoblastic leukemia (ALL), but IRF4 deficiency promotes leukemogenesis in mouse model in cooperation with oncogenes such as BCR-ABL and MYC." (PMID 36495369, 2023).
allergic asthma (6 papers, 2016 to 2025). A asthma with a basis in a pathological type I hypersensitivity reaction. "In allergic airway inflammation, IRF4 is crucial for the regulation of type 2 immune response in mouse model of allergic asthma." (PMID 27007158, 2016). "Therefore, it is essential to decipher the novel mediators involved in regulation of CCR7, IRF-4, and PD-L2 in allergic asthma." (PMID 34185781, 2021). "Similar to PD-L2, expression of IRF-4 is increased in patients with allergic asthma." (PMID 34185781, 2021). "In addition, we tried to shed light on the relationship between NFATc1 and NFATc2 and IRF4, another transcription factor upregulating cytokines like IL‐4 and IL‐9 involved in allergic asthma." (PMID 33079489, 2020). "Tilianin suppresses Th2 immune responses by down-regulating interferon regulatory factor 4 (IRF4) in DCs, therefore mitigating house dust mite-induced allergic asthma." (PMID 41246326, 2025).
colorectal cancer (6 papers, 2016 to 2024). A primary or metastatic malignant neoplasm that affects the colon or rectum. "Hypermethylated markers on IRF4 have been reported as useful for detecting colorectal cancer patients using cfDNA." (PMID 39030645, 2024). "IRF4 overexpression decreases Tregs stability, thereby increasing macrophage‐like transformation of Tregs, repressing the development of colorectal cancer cells, and exacerbating anti‐tumour immunosuppression." (PMID 37341064, 2023). "DMRs residing in four genes, BCAT1, GRASP, IKZF1 and IRF4, exhibited low positivity, 3.5% to 7%, in the plasma of colonoscopy-confirmed healthy subjects, with the sensitivity for detection of ctDNA in colonoscopy-confirmed patients with colorectal cancer being 65%, 54.5%, 67.6% and 59% respectively." (PMID 27983717, 2016).
diabetes (6 papers, 2011 to 2024). "Therefore, this study aimed to evaluate the frequency of Tr1 cells and their association with aryl hydrocarbon receptor (AHR) and interferon regulatory factor-4 (IRF4) gene expression levels in type 1 diabetes mellitus (T1DM) compared to the healthy controls." (PMID 39211721, 2024). "Furthermore, our data suggested that increases in IRF4 expression and CD4+CD8α−CD11c+IRF4+ DCs population in NOD mice were associated with the abnormal function of DCs in diabetes-prone NOD mice." (PMID 21647406, 2011). "The levels of AHR and IRF4 expression were analyzed in both the healthy controls and patients with type 1 diabetes mellitus." (PMID 39211721, 2024). "Together, these results suggested that gene and protein expression levels of IRF4 were upregulated in the spleen of diabetes-prone NOD mice whereas levels of IRF8 remained unchanged at 3 and 7 weeks of age, and were slightly increased in 10 and 20 weeks old mice when compared to BALB/c mice." (PMID 21647406, 2011). "Treatment of BDC mice with αCD3 Ab (clone 2C11), a therapy shown to reverse diabetes in NOD mice, however, decreased expression of Foxo1-axis genes but increased expression of TCR-driven genes (Irf4, Nr4a1, Cd25, Cd69, Tbx21) in PLN BDC CD4+ T cells." (PMID 34314385, 2021). "In the present study, we have investigated the expression of IRF4 and IRF8 genes in splenocytes and DCs of diabetes-prone NOD mice and compared the results to diabetes-resistant NOR and BALB/c mice." (PMID 21647406, 2011). "At the same time, the IRF4 downstream pathways of Notch1 and p-AKT pathways are opened, indicating that diabetes is stimulated by various factors, and IRF4 may promote renal damage." (PMID 35518350, 2022). "Further investigation on the role of IRF4 and IRF8 in diabetes development may help to determine whether IRF4 and/or IRF8 could be potential targets for therapeutic interventions in type 1 diabetes." (PMID 21647406, 2011). "We found that the levels of mRNA expression of IRF4 were slightly but not significantly higher (P > .05) in splenocytes of 3-week old NOD (7.7 ± 0.8) mice as compared to splenocytes of diabetes-resistant BALB/c (1.04 ± 0.1), NOR (2.6 ± 0.6), C57BL/6 (5.8 ± 0.9), or CD1 (3.7 ± 0.8) mice." (PMID 21647406, 2011). "In a first series of experiments, we used quantitative PCR (qPCR) to assess gene expression of IRF4 and IRF8 in splenocytes isolated from prediabetic and diabetic NOD mice as well as control diabetes-resistant congenic NOR and BALB/c mice." (PMID 21647406, 2011).
glioma (6 papers, 2020 to 2025). A benign or malignant brain and spinal cord tumor that arises from glial cells (astrocytes, oligodendrocytes, ependymal cells). "CCL22, IL2RB and IRF4 were found to be competitive endogenous RNAs whose expression intensity may predict the prognosis of glioma patients." (PMID 32667033, 2020). "We performed qRT-PCR analysis and found that the expressions of TNFAIP6, PSMB2, IRF4 and IFNAR2 were significantly upregulated in glioma tissues (n = 30) compared to normal brain tissues (n = 10)." (PMID 36712869, 2022). "Overall survival curves indicated that glioma patients with lower IRF1 (p = 4.42E-33), IRF2 (p = 2.22E-16), IRF3 (p = 1.43E-15), IRF4 (p = 0.004), IRF5 p = 5.84E-12), IRF7 (p = 6.85E-28), IRF8 (p = 0.001), and IRF9 (p = 0.000) transcript levels had significantly longer overall survival times." (PMID 33902005, 2021). "Moreover, the formulation better countered the immunosuppressive glioma microenvironment by reducing M2 macrophage polarization via the suppression of IRF4 transcription and diminished phosphorylation of STAT6, STAT3, and AKT, thereby undermining a key mechanism of glioma immune evasion." (PMID 40284496, 2025).
helminth infection (6 papers, 2015 to 2019). "Moreover, JMJD3 mediates M2 polarization of macrophages in response to helminth infection, in association with transcriptional activation of IRF4 expression due to specific demethylation of H3K27me3 at the promoter region of IRF4 gene." (PMID 29383092, 2017). "CD11b+ conventional IRF4-dependent DC have been shown to coordinate Th2 cell priming following protease inoculation and worm infection in the skin, as well as house dust mite extract installation in the lungs." (PMID 25764512, 2015). "However, as shown for helminth infections and in anti-tumor responses, Irf4−/− mice showed hampered M2 macrophage polarization, when stimulated with IL-4 and IL-13 ex vivo." (PMID 31632388, 2019).
lung carcinoma (6 papers, 2020 to 2025). "In contrast to A4GALT, CIB2, and PSMA1, high expression of IRF4 is associated with higher lung cancer patient survival." (PMID 33227088, 2020). "Taken together these controversial conclusions and our findings, we speculated that the prognostic impact on IRF4 was likely associated with the different sample sources (tumor cell or lymphocyte) in lung cancer." (PMID 34195096, 2021). "Inhibition of IRF4 facilitates the LXR anti-tumor effect; while other studies have shown that IRF4 expression contributes to long OS in lung cancer patients." (PMID 39384770, 2024). "Like CIB2, IRF4 function in lung cancer remains to be clearly determined." (PMID 33227088, 2020). "In addition, RUFY1, DEPDC7, and IRF4 were reported to be involved in lung cancer." (PMID 33051402, 2020). "The detailed functions of IRF2, IRF4, and IRF8 in lung cancer are complex and controversial." (PMID 39384770, 2024).
lymphoid neoplasm (6 papers, 2019 to 2025). A neoplasm composed of a lymphocytic cell population which is usually malignant (clonal) by molecular genetic and/or immunophenotypic analysis. "IRF4 is one of prime examples of oncogenic master transcription factors that has been implicated in various mature lymphoid neoplasms." (PMID 36077849, 2022). "In addition to its roles in normal development and immunity, IRF4 has been implicated as an oncogene in mature lymphoid neoplasms." (PMID 36077849, 2022). "The 2017 World Health Organization (WHO) classification of lymphoid neoplasms introduced for the first time the large B-cell lymphoma with IRF4 rearrangement (LBCL-IRF4) as a provisional entity." (PMID 36810796, 2023). "In this review article, we provide an overview of the molecular functions of IRF4 in mature lymphoid neoplasms and highlight its upstream and downstream pathways, as well as the regulatory circuits mediated by IRF4." (PMID 36077849, 2022). "NF-κB is a critical upstream pathway of IRF4, which is often constitutively activated in various mature lymphoid neoplasms." (PMID 36077849, 2022). "IRF4 exerts its oncogenic effects through the modulation of critical oncogenic transcriptional regulatory networks in mature lymphoid neoplasms." (PMID 36077849, 2022). "IRF4 is a master regulator of immunity and is also frequently overexpressed in mature lymphoid neoplasms." (PMID 35504924, 2022). "On the other hand, IRF4 acts as an oncogene in various mature lymphoid neoplasms when abnormally expressed." (PMID 36077849, 2022). "Genetic knockdown of IRF4 or treatment with IRF4-degrading immunomodulatory drugs (e.g., lenalidomide or pomalidomide) hinders cell proliferation and induces apoptosis in various lymphoid neoplasms in vitro." (PMID 36077849, 2022). "IRF4 is a regulator of immune function, and is overexpressed in lymphoid neoplasms." (PMID 35504924, 2022).
nevus (6 papers, 2018 to 2026). Nevus (or naevus, plural nevi or naevi, from nævus, Latin for "birthmark") is the medical term for sharply circumscribed[1] and chronic lesions of the skin or mucosa. "The most significant SNP identified in this gene is localized in a predicted melanocyte enhancer that binds IRF4: this is intriguing since an IRF4 SNP (rs12203592) has been associated with nevus count, skin pigmentation, and tanning response." (PMID 40869905, 2025). "Regarding cutaneous nevi, significant associations were identified between the IRF4 gene (P = 4.19 × 10−14) and the MC1R gene (P = 8.64 × 10−4), also as previously published." (PMID 40261663, 2025). "The analysis confirmed previously established nevus-associated loci (MTAP, PLA2G6, IRF4) and uncovered novel associations with single-nucleotide polymorphisms (SNPs) in KITLG and a region on chromosome 9q32." (PMID 41596618, 2026). "In the parallel analysis with pigmentation (indexed by dark hair color), only IRF4 overlapped with nevus count." (PMID 30429480, 2018).
type 1 diabetes (6 papers, 2011 to 2025). "IRF4 is one candidate gene located in the idd14 susceptibility region suspected to play a role in the development of type 1 diabetes in NOD mice." (PMID 21647406, 2011). "Blimp-1 and IRF4 can be activated by factors other than B cell receptor signalling, such as IL-21 and IL-6 or IFNα and IL-6, cytokines implicated in the pathogenesis of type 1 diabetes." (PMID 36508037, 2023). "Overactivation of IRF4 has been associated with increased secretion of diabetogenic cytokines by CD4 + T cells, promoting the development of type 1 diabetes." (PMID 40597598, 2025). "Our results showed that IRF4 expression was up-regulated in NOD mice and correlated with the increased levels of CD4+CD8α− DCs, suggesting that IRF4 may be involved in abnormal DC functions in type 1 diabetes in NOD mice." (PMID 21647406, 2011). "Our data reported an enhanced involvement of the IRF4 and IRF8 in DCs function in type 1 diabetes-susceptible NOD mice as opposed to control, nondiabetic mice." (PMID 21647406, 2011).
Whipple disease (6 papers, 2018 to 2026). A systemic infection caused by the Gram-positive bacterium Tropheryma whipplei. "IRF4 deficiency was identified as an AD cause of Whipple disease with (unexplained) incomplete penetrance." (PMID 34867986, 2021). "We report two patients with Whipple’s disease caused by autosomal dominant IRF4 deficiency." (PMID 41424747, 2026). "IRF4 haploinsufficiency is an autosomal dominant IEI and defect of innate immunity affecting leukocytes and macrophages which confers susceptibility to the rare bacterial infection Whipple's disease." (PMID 39241920, 2024). "The impaired migration of Irf4 heterozygous T cells to the intestine and possible to other peripheral tissues could also explain the detection of several cases of Whipple's disease in an Irf4 haploinsufficient kindred." (PMID 37469513, 2023).
experimental autoimmune encephalomyelitis (5 papers, 2016 to 2025). An autoimmune demyelinating disease of the central nervous system that is produced experimentally in animals by the injection of homogenized brain or spinal cord in Freund's adjuvant. "Notably, IRF4 up-regulation of MHC class II molecules was shown by these investigators to be strongly associated with disease severity in a murine model of experimental autoimmune encephalomyelitis (EAE)." (PMID 26880555, 2016). "For example, CD11c+ DCs from the IRF4 siRNA-treated mice showed significantly decreased inflammatory cytokines including IL-23, resulting in ameliorating experimental autoimmune encephalomyelitis in IRF4 siRNA-treated mice." (PMID 32456211, 2020). "CD16+ monocytes showed downregulation of select transcription factor genes (RXRA, IKZF1, KLF4, IRF4) and CD81, a marker that facilitates monocytes homing to the CNS in experimental autoimmune encephalomyelitis (EAE)." (PMID 40067358, 2025). "In IRF4 research on the role of Th17 cell differentiation, Brüstle found that mice knockout IRF4 failed to develop experimental autoimmune encephalomyelitis, T cell and RORgamma T were expressed lower, and Th17 cell differentiation was impaired." (PMID 28808358, 2017).
gastric cancer (5 papers, 2016 to 2023). A primary or metastatic malignant neoplasm involving the stomach. "We also observed a statistically significant association between gastric cancer diagnosis and promoter methylation of IRF4, ELMO1, CLIP4 and MSC, after adjusting for age and sex." (PMID 28418867, 2017). "In agreement with our results in primary gastric cancers, KLF2pos xenografts had high expression of plasma cell markers IRF4 and SLAMF7 in the humanized mice only, reflecting increased plasma cell recruitment associated with KLF2." (PMID 34642171, 2022). "Our findings suggest that IRF4, ELMO1, CLIP4 and MSC promoter methylation coupled with a GDMI>4 are useful molecular tools for gastric cancer risk stratification in endoscopic biopsies." (PMID 28418867, 2017). "Our findings suggest that promoter methylation of CLIP4, IRF4, ELMO1, and MSC, together with a GDMI > 4, is a useful molecular panel for gastric cancer risk stratification in endoscopic biopsies." (PMID 28418867, 2017). "Interferon regulatory factor 4 (IRF4) was found to be highly silenced by DNA hypermethylation in both gastric cancers and gastric mucosa from cancer patients, which suggested that IRF4 hypermethylation may be a useful molecular marker for diagnosing recurring gastric cancer." (PMID 27453436, 2016). "For example, miR-877 inhibits progression of gastric cancer by down-regulating AQP3, and miR-125b induces bone marrow and B-cell leukemia by inhibiting IRF4, indicating that many up-regulated miRNAs in CML samples may inhibit the expression of target genes." (PMID 37024911, 2023). "Together these results suggest that promoter methylation of IRF4, ELMO1, CLIP4 and MSC may be part of a gastric cancer CpG island methylator phenotype (CIMP)." (PMID 28418867, 2017). "Promoter methylation of IRF4 (p < 0.0001), ELMO1 (p < 0.0001), CLIP4 (p < 0.0001), and MSC (p < 0.0001), is also associated with increasing severity from gastritis with no metaplasia to gastritis with metaplasia and gastric cancer." (PMID 28418867, 2017). "The promoter methylation of IRF4, ELMO1, CLIP4, and MSC is related with increasing seriousness from gastritis with no metaplasia to gastritis with metaplasia and gastric cancer." (PMID 33575272, 2020).
hepatocellular carcinoma (5 papers, 2013 to 2025). A malignant tumor that arises from hepatocytes. "By comparing the mRNAs in the ceRNA subnetwork with the mRNAs in the PPI subnetwork, three common mRNAs (ESR1, CXCL12 and IRF4) were obtained, which should play an important role in the development of hepatocellular carcinoma and used as follow-up research objects." (PMID 36855431, 2023). "miR-99b has also been reported to suppress M2 macrophage polarization by repressing the mTOR/IRF4 axis, leading to tumor regression characterized by increased CD8+ T-cell infiltration and reduced MDSC and Treg populations in hepatocellular carcinoma." (PMID 41550951, 2025).
influenza (5 papers, 2020 to 2025). An acute viral infection of the respiratory tract, occurring in isolated cases, in epidemics, or in pandemics; it is caused by serologically different strains of viruses (influenzaviruses) designated A, B, and C, has a 3-day incubation period, and usually lasts for 3 to 10 days. "However, other studies have now implicated IRF4-dependent cDC2 in lung TRM formation after influenza infection." (PMID 33042159, 2020). "Here we show that Irf4−/− mice fail to mount a productive pulmonary Tγδ17 cell response during influenza challenge." (PMID 33772013, 2021). "We chose to analyze the differentiation of human B cells based on the bifurcated expression patterns of the activation-induced TFs, IRF4 and IRF8, which are observed in the murine system and also in human HA-specific B cells that emerge within one week of influenza immunization." (PMID 40667223, 2025). "Notably, IRF4 and XBP1 emerge as hub proteins that exhibit multifunctional properties, and diminishing their expression levels could potentially hinder the efficacy of the humoral immune response to the influenza vaccine." (PMID 38400120, 2024).